CDH1 (cadherin 1)
Diseases named in the same sentence as CDH1 in open-access papers (continued):
Sharing a sentence is not in itself a finding about the gene and the disease.
tumor (continued). "Since the protein level of E-cadherin was increased in the SG-/- tumour tissue we next checked the transcriptional level of Cdh1 on the microarrays." (PMID 27223472, 2016). "In our study, CDH1 was one of seven EMT-associated genes (CDH1, SCD, PAPSS2, C3orf52, FREM, SLC22A24, SLC25A29) successfully validated to be deregulated in tumor tissue." (PMID 27549611, 2016). "In our study, we evaluated ccRCC tumor tissues by immunofluorescence staining of common EMT markers (CDH1, CK18, CK19, VIM, S100A4) and stratified patients to EMT positive and EMT negative groups." (PMID 27549611, 2016). "Although the importance of CDH1 inactivation for tumor metastasis has been well demonstrated in several studies, its mutation frequency was not significantly high and was <10% across all data sets." (PMID 27625789, 2016). "Several of these genes can also be considered as marker of tumor differentiation or contribute to epithelial-to-mesenchymal transition (EMT) such as CDH1, EDN1 or ERBB2 for instance." (PMID 27509260, 2016). "CDH1 is a tumor suppressor gene, and therefore a somatic second hit is required for initiation of tumor formation." (PMID 27512640, 2016). "Promoter hypermethylation is considered to be a mechanism of HNSCC progression, although analysis has been limited to a small number of tumor-suppressor genes, such as p16, CDH1, RARβ, MGMT, DAPK, DCC, GALR1, and GALR2." (PMID 26823082, 2016). "This genetic evidence was further supported by recent studies revealing a decrease of Cdh1 expression in various human tumor tissues." (PMID 27462441, 2016). "Gene expression measures for CDH1 shows very high evidence of within-patient between-tumor heterogeneity (73.8% heterogeneity, p = 3.16x10-9)." (PMID 27078887, 2016). "Using the methylation PCR array, we have demonstrated that overexpression of ERp29 resulted in hypomethylation of CpG islands in tumour suppressor genes such as CDH1, p16 and MGMT, thereby leading to upregulation of these genes." (PMID 26420420, 2015). "Hypermethylation was associated with advanced tumor grade for BRCA1 (P = 0.003), CDH1 (P = 0.002), HSPA2 (P = 0.009), RASSF1A (P = 0.017), and THBS1 (P = 0.000), while methylated GDF15 (P = 0.002) promoter was associated with low tumor grade." (PMID 25613404, 2015). "Suppression of CDH1 expression is one of the primary molecular events responsible for dysfunction in cell-cell adhesion, such as that which occurs in tumor progression." (PMID 25978455, 2015). "Under this controlled condition, it can be clearly seen that in NCA sections CDH1 mRNA was also clearly visible in the cytosol, whereas in all tumorous tissue areas staining for CDH1 mRNA was completely shifted to the nucleus." (PMID 26029826, 2015). "TWIST1, a highly conserved basic helix-loop-helix (bHLH) transcription factor that represses E-cadherin (CDH1) transcription, represents an EMT inducer and has been convincingly associated with tumor progression and the metastatic process." (PMID 26198055, 2015). "The expression of CDH-1 was influenced by tumor malignancy and cycle stage, i.e., the highest gene expression was found in benign mammary tumors in diestrous dogs compared to normal and malignant mammary tissues of anestrous and spayed dogs." (PMID 26370564, 2015). "Tumor biopsies were methylated in 1/5 (20 %), 2/5 (40 %), 4/5 (80 %), and 4/5 (80 %) for the CDH1, CDKN2A, DAPK, and TIMP2 genes, respectively." (PMID 26363785, 2015). "Although conventional Cdh1 knockout was of little immediate value for elucidating the tumor suppressor function of E-cadherin, it inspired many decisive studies on the important roles of E-cadherin in murine embryonic stem cells and embryonic development." (PMID 25757734, 2015).
tumor (continued). "A prominent EMT feature is the downregulation of the tumour-and-invasion suppressor E-cadherin (Cdh1), which enables a cell to dissolve its cell–cell contacts and break away from its neighbours." (PMID 25492890, 2015). "While the levels of CDH1 remained unchanged, Snail levels actually decreased in the tumors compared to the parental or explanted tumor cells grown in vitro for both NPC and GaCa." (PMID 25590614, 2015). "Chromosome 16q contains several tumor suppressor genes, including E-cadherin (CDH1), a member of the calcium-dependent adhesion family of transmembrane proteins." (PMID 26041550, 2015). "We also observed that cancer cell expression of CDH1/IL-1β is predictive for the presence of significant biological effects of hMSCs on tumor cells." (PMID 26204886, 2015). "CTCF insulates and shields tumour suppressor genes, like Cdh1, p16 and RASSF1A, from being epigenetically silenced in cancers; on the other hand, when such DNA loci become methylated, CTCF gets repelled or is unable to bind anymore." (PMID 25492890, 2015). "Our previous studies showed that overexpression of ERp29 significantly increased the expression of tumour suppressors, such as E-cadherin (CDH1), at both mRNA and protein levels." (PMID 26420420, 2015). "CDH1 germline mutations are associated with the hereditary DGC syndrome and ILC belongs to the tumor spectrum in these patients." (PMID 25757734, 2015). "Based on the staining intensity, BMP-4 and CDH1 demonstrated a higher protein expression and/or increased positivity in lung metastases when compared with the primary tumor tissues." (PMID 26059540, 2015). "Tumor biopsies were methylated in 1/5 (20 %), 2/5 (40 %), 4/5 (80 %), and 4/5 (80 %) for CDH1, CDKN2A, DAPK, and TIMP2 genes, respectively." (PMID 26363785, 2015). "Hypermethylation was associated with advanced tumor stage for ABCC6 (P = 0.050), BRCA1 (P = 0.032), CDH1 (P = 0.004), GDF15 (P = 0.005), HSPA2 (P = 0.000), RASSF1A (P = 0.003), TSHB1 (P = 0.018), and TMEFF2 (P = 0.002)." (PMID 25613404, 2015). "Follow-up studies showed that Cdh1 inactivation releases p120 from AJs to the cytosol and nucleus, where it controls tumor progression through distinct and druggable signaling pathways." (PMID 25757734, 2015). "Our results show that the CDH1 promoter methylation in tumor tissue was lower than in the adjacent margins." (PMID 26363785, 2015). "It is interesting to note that mice heterozygous for E-cadherin (Cdh1+/−) have an increased tumour burden when crossed to the Apc1638N/+ mouse model, a long latency model of Apc-loss induced tumourigenesis." (PMID 26240067, 2015). "Here, the tumour suppressor CDH1 is responsible for maintaining cell adhesion and regulating cell migration." (PMID 26427375, 2015). "MED30 induced the expressions of EMT-related genes (N-cadherin; CDH2, P-cadherin; CDH3, twist related protein 1 and 2; TWIST1/2, vimentin; VIM), but inhibited the expression of E-cadherin (CDH1) a known tumor suppressor." (PMID 26110885, 2015). "In these studies, CDH1 loss and overexpression of SNAI1, TWIST1 and LAMC2 were observed at the invasive front of the tumors, particularly in single or cords of tumor cells detaching from the tumor mass." (PMID 26214683, 2015). "When comparing differentially expressed genes between the two cell groups, we observed CDH1 to be among the top genes highly expressed by the positive tumor group." (PMID 26204886, 2015). "The alterations of EMT-associated markers, such as: loss of epithelial genes CDH1, CDH3 and gain of mesenchymal genes CDH2 and FN1, as well as the adoption of a migratory mesenchymal phenotype were maintained in all the tumor-derived cell lines." (PMID 25361000, 2014).
tumor (continued). "In contrast to the tumor suppressive functions of miR-200 and miR-34, the miR-9 family appears to be tumor activating through a direct interaction with the CDH1 promoter which subsequently initiates EMT." (PMID 25343018, 2014). "Previous studies have shown that the downregulation of CDH1 is an important feature of a number of transformed cells, and that CDH1 functions as a tumor suppressor." (PMID 24520301, 2014). "Unexpectedly, we found the core promoter regions of two tumor suppressor genes, CDH1 and SFN, were demethylated in three EAC samples." (PMID 25286960, 2014). "In these cancers, the methylation of the promoter regions of tumor suppressor genes, such as CDH1, APC, MGMT, RASSF1A, GSTP1, p16 and RAR-β2, affect the activity of tumor suppressor genes, typically leading to transcriptional silencing." (PMID 24748968, 2014). "Coincident with findings that calcitriol slowed tumor growth; a significant increase in CDH1 expression was observed." (PMID 24586868, 2014). "In fact, in early single-gene analysis, tumor suppressor genes including P16, CDH1 and GSTP1 were found to be hypermethylated in HCC." (PMID 25093504, 2014). "In our study, many TSGs had hypermethylation in their core promoter regions, but interestingly, two tumor suppressor genes (CDH1 and SNF) were found to have hypomethylated promoters and increased mRNA expression." (PMID 25286960, 2014). "In various types of cancer, CDH1-mediated cell-cell adhesion is lost concomitantly with acquisition of an invasive phenotype, high tumor grade and low patient survival rates." (PMID 24520301, 2014). "Screenings as done herein exemplarily for the HMGA2 regulator let-7a and the HMGA2 targets HMGA1, SNAI1, SNAI2 and CDH1 will help to reveal the tumour acting mechanisms." (PMID 24914948, 2014). "In both LBC and DGC, CDH1 inactivation can be an early initiating event, whereas in other tumour types including prostate, lung, ovarian and colon, its downregulation is usually considered to be a late event that promotes an increase in invasive capacity." (PMID 25079037, 2014). "The tumor suppressor gene and epithelial cell marker E-cadherin (Cdh1) was markedly up-regulated and the oncogenic transcription factor Myc was down-regulated by Tcf7l2 silencing." (PMID 25414334, 2014). "Several represented genes, TIMP3, p16 (CDKN2A), p14, MGMT, CDH1, RASSF1A and DAPK, are highly sensitive to methylation-induced repression in HNSCC tumor and saliva samples, and are directly associated with tumor development." (PMID 25587491, 2013). "Considering the correlation among specific CDH1 germline alterations and the tumor histotype, we found that 8.3% (1 of 12 GCs) of mixed (ID11) and 7.7% (2 of 26 GCs) of diffuse (ID17) subtypes, carried a potential pathogenic mutation." (PMID 24204729, 2013). "Further, Cdh1/Fzr heterozygous mice displayed an increased propensity to develop epithelial tumors, suggesting a tumor suppression function for Cdh1/Fzr." (PMID 24086162, 2013). "Kaplan–Meier analysis showed that patients with CDH1 unmethylation in tumor tissues or in PPW exhibited an obvious survival advantage (both P = 0.000)." (PMID 22514028, 2012). "CDH1 belongs to a family of genes directly related to the processes of tumor invasion and cytoskeleton destabilization." (PMID 22794276, 2012).
tumor (continued). "In confirmation of our in vitro data on CDH1 up-regulation, we also noted an increase in CDH1 on the periphery of the primary tumor from our MDA-MB-231 xenograft model." (PMID 22613095, 2012). "For example, several miRNAs, including the miR-17-19b cluster, and genes, including CDH1, have been shown to have oncogenic properties in some cancer types while acting as tumor suppressors in others." (PMID 23091610, 2012). "The overexpression of APC-Cdh1 substrates has been correlated with different types of malignant tumor, implying that Cdh1 plays a pivotal tumor-suppressing role." (PMID 22479455, 2012). "In particular, 12 genes, including AXL, CDH1, CFLAR, FKBP1A, NT5E, and VIM, were reported to be significantly associated with tumor metastasis (P<8E-04)." (PMID 23185353, 2012). "This increased CDH1 was confirmed with measured upregulation of the CDH1 staining at the primary tumor periphery in our xenograft model." (PMID 22613095, 2012). "Multivariate Cox regression analysis indicated that tumor recurrence, low-level of miR-214 and CDH1, and high-level of EZH2 and CTNNB1 were prognostic factors for early HCC recurrence and poor survival." (PMID 22962603, 2012). "LOXL2 has been found to act in the nucleus of cancer cells and deaminates the lysine 4 amino group of H3 leading to downregulation of CDH1, decreased E-cadherin expression, fewer cellular adhesions facilitating tumour growth and metastases." (PMID 23125850, 2012). "The constitutive expression of SNAI1 and CDH1 in RB tumor tissues revealed the inverse correlation between them." (PMID 23077401, 2012). "In relation to the degree of tumor differentiation, it was observed that CDH1 presented a high methylation frequency in poorly differentiated tumors and in cases with three or more positive nodes." (PMID 22794276, 2012). "It was observed CDH1 methylation in tumor tissues from GC patients whose PPW were detected CDH1 methylation." (PMID 22514028, 2012). "On the contrary, CDH1 inactivation results in decreased cell adhesion and abnormal polarity, which promotes tumor metastasis 13–16." (PMID 22514028, 2012). "Unexpectedly, one of the most significantly dysregulated genes within the CMP and GMP compartments was Cadherin 1 (Cdh1), a tumor suppressor in epithelial cancers, which was strikingly up-regulated in both the CMP and GMP compartments of Ctsg-PML-RARA mice." (PMID 23056333, 2012). "Accordingly, expression of hallmark EMT genes such as Snai1/Snail1 and Fn1 was downregulated in the presence of a JNK inhibitor in conditions that increased expression of the Cdh1 gene in Amela tumor lines." (PMID 23173060, 2012). "With regard to PCa, correlations between decreased CDH1 expression and prognostic factors including tumor grade, stage and ploidy, have been reported." (PMID 22547956, 2011). "Both, during development and in tumors, EMT signals are frequently integrated by transcriptional repressors of CDH1, such as Snail, Snail2, Twist and others, which thus play important roles in the control of cell morphology and tumor progression." (PMID 21853123, 2011). "The highest expression of SNAI2, TWIST1, VIM and lowest expression of CDH1 was found in the CCND1low/ID1high subgroup of tumours (yellow bars)." (PMID 21955753, 2011). "The second connection including RAB25, SNAI1, and CDH1 was suggested to be related to tumor invasion." (PMID 20142997, 2010). "The connection including TGM2, IL1B, and PLAU and the connection including RAB25, SNAI1, and CDH1 were suggested to be related to tumor invasion by IPA." (PMID 20142997, 2010). "In a study recently published, basal-like tumour cell lines were characterized by the concomitant hypermethylation of a six gene panel (CDH1, CEACAM6, CST6, ESR1, LCN2, SCNN1A)." (PMID 20338046, 2010). "Cowin et.al. provided evidence that CDH1 serves both as a tumor suppressor and an invasion suppressor in an animal model of invasive lobular breast cancer (ILC)." (PMID 19636430, 2009).
tumor (continued). "E-cadherin gene (CDH1) is considered a tumor and invasion suppressor gene, since its down-regulation enhance cell migration and promotes metastasis in a variety of cancer models." (PMID 19257890, 2009). "Cadherin 1 (CDH1) is a suppressor of tumor invasion and metastasis, cellular adhesion, antagonist of ß-catenin/Wnt signaling and interferes with growth factor signaling." (PMID 19578441, 2009). "Inactivation of the cdh1 mediated cell adhesion system was a common finding in human cancers, indicating that cdh1 function as tumor suppressor and invasion suppressor genes." (PMID 19397828, 2009). "CDH2 enhances tumor cell motility and migration and has been postulated to exert a dominant effect over CDH1 function." (PMID 19636430, 2009). "SNAI2, Zeb2 and other family members have multiple gene targets and can recruit specific chromatin-remodelling complexes that repress E-cadherin (CDH1), which is frequently downregulated in tumor progression and EMT and implicated in lymph node metastasis." (PMID 18638373, 2008). "In our MSP analysis performed on DNA obtained from fresh tumor samples, a hypermethylated pattern predominated for CDH1 and SFN genes." (PMID 18702824, 2008). "It will also be necessary to use model organisms to investigate how much E2F regulation contributes to pRB's role as a tumor suppressor compared with Cdh1/Skp2 or others." (PMID 17854503, 2007). "Specifically, CDH1 and RASSF1A promoter hypermethylation levels were inversely associated with tumor stage (p = 0.031) and nuclear grade (p = 0.022), respectively." (PMID 17645803, 2007). "Does this implicate Cdh1/Skp2 binding in tumor suppression because it is part of the proliferative control mechanism that functions in the absence of E2F control in the R661W mutant?" (PMID 17854503, 2007). "Hypermethylation of MGMT (in 14 tumours), CDH1 (in nine tumours), RAR-β (in eight tumours) and SYK (in seven tumours) have been found." (PMID 14970867, 2004). "DECMA-1 is also used in studies targeting CDH1 in tumor xenograft models." (PMID 41459333, 2026). "CDH1 expression is notably reduced in tumor tissues compared to normal tissues." (PMID 40757085, 2025). "Prior research has demonstrated that the nuclear export of PTEN, rather than the inhibition of its phosphatase activity, compromises the activation of the anaphase promoting complex/cyclosome (APC)-CDC20like protein 1 (CDH1) complex, consequently reducing its tumor-suppressive function." (PMID 40243588, 2025). "Additionally, the University of Alabama at Birmingham cancer data analysis portal (UALCAN) was used to evaluate CDH1 gene expression in tumor versus normal tissues within the TCGA-BRCA dataset." (PMID 40757085, 2025). "Notably, CDH1–an adhesion molecule governing epithelial integrity–appears prominently, further highlighting the interplay between tumor architecture, immune infiltration and therapeutic responsiveness." (PMID 40745034, 2025). "Therefore, therapeutic strategies must be carefully designed to selectively inhibit pro-tumor cadherins while preserving or restoring the tumor-suppressive function of CDH1." (PMID 40860670, 2025). "Approximately 17% of mutation-negative familial GCs show CDH1 promoter methylation in the tumor, contributing to E-cadherin loss." (PMID 41097736, 2025). "Furthermore, tumour‐derived PCS combined with Cdh1 to enhance Bnip3‐dependent mitophagy activity of Tim4 positive tumour‐associated macrophages (TAMs)." (PMID 40604335, 2025). "Dot plots demonstrate differential gene expression between the four tumor cell types (Biphasic_glands, Biphasic_spindled, Monophasic and Poorly differentiated), showing an inverse correlation between the expression of CDH1 (high in Biphasic_glands) and SNAI2 (low in Biphasic_glands)." (PMID 41440042, 2025). "Additionally, the clinical relevance of CDH1 upregulation warrants investigation across tumor stages and subtypes." (PMID 40693059, 2025).